AP3M1 (adaptor related protein complex 3 subunit mu 1)
Description:
Part of the AP-3 complex, an adaptor-related complex which is not clathrin-associated. The complex is associated with the Golgi region as well as more peripheral structures. It facilitates the budding of vesicles from the Golgi membrane and may be directly involved in trafficking to lysosomes. In concert with the BLOC-1 complex, AP-3 is required to target cargos into vesicles assembled at cell bodies for delivery into neurites and nerve terminals.
Tractability: Small molecule: a structure with a bound ligand is known. Antibody: UniProt places it where antibodies can reach, with medium confidence. PROTAC: ubiquitination databases record sites on it; its protein half-life has been measured.
Gene: Protein-coding gene on chromosome 10 (74,120,255 to 74,151,055, reverse strand). Ensembl gene ENSG00000185009.
Subcellular location: Golgi apparatus; Cytoplasmic vesicle membrane
Pathways (Reactome):
Metabolism of proteins: Association of TriC/CCT with target proteins during biosynthesis
Gene Ontology:
Molecular function: protein binding; small GTPase binding; clathrin adaptor activity; AP-3 adaptor complex binding
Biological process: anterograde axonal transport; anterograde synaptic vesicle transport; clathrin-coated vesicle cargo loading, AP-3-mediated; endocytosis; Golgi to vacuole transport; melanosome assembly; platelet dense granule organization; protein targeting to lysosome; vesicle-mediated transport; intracellular protein transport; postsynaptic neurotransmitter receptor internalization
Cellular component: lysosomal membrane; AP-3 adaptor complex; early endosome; lysosome; axon cytoplasm; clathrin adaptor complex; cytoplasmic vesicle membrane; Golgi apparatus; postsynaptic recycling endosome
Genetic constraint (gnomAD): Loss-of-function variants: 22 observed, 38.15 expected, observed/expected ratio (o/e) 0.58, 90% interval 0.41 to 0.82. The upper end of that interval is the gene's LOEUF score, 0.82, which puts it in group 3 of 6, group 1 being the genes least tolerant of losing a copy. Missense variants: 388 observed, 487.54 expected, observed/expected ratio (o/e) 0.8, 90% interval 0.73 to 0.87. Synonymous variants: 163 observed, 169.16 expected, observed/expected ratio (o/e) 0.96, 90% interval 0.85 to 1.1.
Homologues: Orthologues: chimpanzee AP3M1 (100% identical), dog AP3M1 (100% identical), guinea pig AP3M1 (99% identical), macaque AP3M1 (99% identical), mouse Ap3m1 (99% identical), pig AP3M1 (99% identical), rabbit AP3M1 (99% identical), rat Ap3m1 (99% identical), zebrafish ap3m1 (82% identical), Caenorhabditis elegans apm-3 (63% identical). Paralogues in human: AP3M2 (84% identical), AP1M2 (31% identical), AP1M1 (29% identical), AP2M1 (25% identical), AP4M1 (20% identical), STON2 (18% identical), STON1 (17% identical).
Diseases named in the same sentence as AP3M1 in open-access papers:
AP3M1 is named in the same sentence as 3 diseases in open-access papers, as found by Europe PMC text mining. Sharing a sentence is not in itself a finding about the gene and the disease. The quoted sentences say what the papers report.
Intellectual disability (1 paper, 2023). "RNS neurophenotypes share some features with AP3B1 and AP3M1 LoF, including development delay/intellectual disability, seizures, and hypotonia." (PMID 37240249, 2023).
AP3M1 also shares sentences with these, for which no sentence is quoted: cancer (1 paper); liver cancer (1).